GSK3A (glycogen synthase kinase 3 alpha)
Description:
Constitutively active protein kinase that acts as a negative regulator in the hormonal control of glucose homeostasis, Wnt signaling and regulation of transcription factors and microtubules, by phosphorylating and inactivating glycogen synthase (GYS1 or GYS2), CTNNB1/beta-catenin, APC and AXIN1. Requires primed phosphorylation of the majority of its substrates. Contributes to insulin regulation of glycogen synthesis by phosphorylating and inhibiting GYS1 activity and hence glycogen synthesis. Regulates glycogen metabolism in liver, but not in muscle (By similarity). May also mediate the development of insulin resistance by regulating activation of transcription factors. In Wnt signaling, regulates the level and transcriptional activity of nuclear CTNNB1/beta-catenin. Facilitates amyloid precursor protein (APP) processing and the generation of APP-derived amyloid plaques found in Alzheimer disease. May be involved in the regulation of replication in pancreatic beta-cells (By similarity). Is necessary for the establishment of neuronal polarity and axon outgrowth (By similarity). Through phosphorylation of the anti-apoptotic protein MCL1, may control cell apoptosis in response to growth factors deprivation (By similarity). Acts as a regulator of autophagy by mediating phosphorylation of KAT5/TIP60 under starvation conditions which activates KAT5/TIP60 acetyltransferase activity and promotes acetylation of key autophagy regulators, such as ULK1 and RUBCNL/Pacer. Negatively regulates extrinsic apoptotic signaling pathway via death domain receptors. Promotes the formation of an anti-apoptotic complex, made of DDX3X, BRIC2 and GSK3B, at death receptors, including TNFRSF10B. The anti-apoptotic function is most effective with weak apoptotic signals and can be overcome by stronger stimulation (By similarity). Phosphorylates mTORC2 complex component RICTOR at 'Thr-1695' which facilitates FBXW7-mediated ubiquitination and subsequent degradation of RICTOR.
Tractability: Small molecule: an approved drug acts on it; a structure with a bound ligand is known; a high-quality ligand is known; it belongs to a druggable protein family. PROTAC: it is named in the literature on targeted protein degradation; ubiquitination databases record sites on it; its protein half-life has been measured; a small molecule that binds it is known.
Target class: Protein Kinase; CMGC protein kinase group; Enzyme; Kinase; CMGC protein kinase GSK family
Chemical probes: BI-5521 (high quality), CHIR-99021 (high quality), LY-2090314 (high quality), PF-367 (high quality), PT-65, SB-216763 (high quality), SGC-CDKL5/GSK3-1 (high quality), SGC-GSK3-1 (high quality), Tideglusib
Safety:
Unwanted effects reported when the protein is acted on. In parentheses: how it was acted on, where the effect was seen, and who reports it.
heart disease (cardiovascular system; source: Force et al. (2011))
Gene: Protein-coding gene on chromosome 19 (42,226,225 to 42,242,625, reverse strand). Ensembl gene ENSG00000105723.
Subcellular location (Human Protein Atlas): Nucleoplasm; Cytosol
Pathways (Reactome):
Disease: Constitutive Signaling by AKT1 E17K in Cancer; Maturation of nucleoprotein; Suppression of apoptosis
Cellular responses to stimuli: XBP1(S) activates chaperone genes
Signal Transduction: AKT phosphorylates targets in the cytosol
Gene Ontology:
Molecular function: protein binding; protein kinase A catalytic subunit binding; protein serine kinase activity; protein serine/threonine kinase activity; signaling receptor binding; tau protein binding; tau-protein kinase activity; ATP binding; protein kinase activity
Biological process: cellular response to insulin stimulus; negative regulation of D-glucose import; negative regulation of insulin receptor signaling pathway; positive regulation of amyloid-beta formation; positive regulation of establishment of protein localization to mitochondrion; positive regulation of proteasomal ubiquitin-dependent protein catabolic process; positive regulation of protein ubiquitination; regulation of mitophagy; beta-arrestin-dependent dopamine receptor signaling pathway; cardiac left ventricle morphogenesis; cellular response to interleukin-3; excitatory postsynaptic potential; extrinsic apoptotic signaling pathway; extrinsic apoptotic signaling pathway in absence of ligand; insulin receptor signaling pathway; negative regulation of canonical Wnt signaling pathway; negative regulation of cell growth involved in cardiac muscle cell development; negative regulation of glycogen biosynthetic process; negative regulation of TOR signaling; negative regulation of type B pancreatic cell development; positive regulation of adenylate cyclase-activating adrenergic receptor signaling pathway; positive regulation of adenylate cyclase-activating G protein-coupled receptor signaling pathway; positive regulation of autophagy; positive regulation of gene expression; positive regulation of heart contraction; and 13 more
Cellular component: apical dendrite; axon; beta-catenin destruction complex; cytosol; neuronal cell body; proximal dendrite; postsynapse
Genetic constraint (gnomAD): Loss-of-function variants: 9 observed, 37.26 expected, observed/expected ratio (o/e) 0.24, 90% interval 0.14 to 0.42. The upper end of that interval is the gene's LOEUF score, 0.42, which puts it in group 1 of 6, group 1 being the genes least tolerant of losing a copy. Missense variants: 387 observed, 495.19 expected, observed/expected ratio (o/e) 0.78, 90% interval 0.72 to 0.85. Synonymous variants: 265 observed, 220.55 expected, observed/expected ratio (o/e) 1.2, 90% interval 1.09 to 1.33.
Homologues: Orthologues: chimpanzee GSK3A (99% identical), rat Gsk3a (97% identical), dog GSK3A (97% identical), pig GSK3A (96% identical), mouse Gsk3a (95% identical), guinea pig GSK3A (92% identical), rabbit GSK3A (78% identical), zebrafish gsk3ab (73% identical), zebrafish gsk3aa (72% identical), tropical clawed frog gsk3a (68% identical), Drosophila melanogaster sgg (66% identical), Caenorhabditis elegans gsk-3 (53% identical), and 1 more. Paralogues in human: GSK3B (67% identical).
Diseases named in the same sentence as GSK3A in open-access papers:
GSK3A is named in the same sentence as 140 diseases in open-access papers, as found by Europe PMC text mining. Sharing a sentence is not in itself a finding about the gene and the disease. The quoted sentences say what the papers report.
acute myeloid leukemia (16 papers, 2014 to 2025). Acute myeloid leukemia (AML) is a group of neoplasms arising from precursor cells committed to the myeloid cell-line differentiation. "Most studies have focused on the role of total GSK-3 or GSK-3β, but recent studies implicated the oncogenic role of GSK-3α in acute myeloid leukemia (AML), prostate cancer, and pancreatic cancer." (PMID 27049759, 2016). "Previous studies have demonstrated the dysregulation or dysfunction of GSK3A in breast cancer, oral cancer, and acute myeloid leukemia." (PMID 34607506, 2022). "In the setting of acute myeloid leukemia (AML), higher levels of β-catenin, Ser675-phospho-β-catenin and GSK-3α were found in AML cells from intermediate- or poor-risk patients and the patients presenting with a higher activity of Wnt/β-catenin showed a shorter progression-free survival." (PMID 35723395, 2022). "GSK3α-specific inhibition weakens leukemia initiation and prolongs survival in acute myeloid leukemia (AML) mouse models." (PMID 33672232, 2021). "One study initially reported a novel scorpion-shaped molecule with high selectivity towards GSK-3α, and improved derivates of this molecule exhibited anti-cancer activity in treating acute myeloid leukemia (AML)." (PMID 33572709, 2021). "Results from preclinical studies suggest that isoform-targeted inhibition of macrophage GSK3α or GSK3β may be effective in the treatment of acute myeloid leukemia and atherosclerosis." (PMID 33672232, 2021). "Recent evidence suggests that GSK3α and GSK3β play distinct roles in sperm motility and fertility, amyloid production in the brain, cortical development, atherosclerosis development, and acute myeloid leukemia development." (PMID 34394077, 2021). "Based on this idea, the following sections present evidence that supports the importance of GSK3α in neurodegenerative disorders (ND) and brain cancer, pancreatic ductal adenocarcinoma, prostate cancer, acute myeloid leukemia, multiple myeloma, and lung cancer." (PMID 33339170, 2020). "GSK3α has been identified as a new target in the treatment of acute myeloid leukemia (AML)." (PMID 30679640, 2019). "Tivantinib is reported as a more prominent GSK3α and GSK3β inhibitor and a weak MET inhibitor in acute myeloid leukemia." (PMID 39458991, 2024). "In U937 cells (an acute myeloid leukemia cell line), a complex of N-Myc downstream-regulated gene 2 (NDRG2), GSK3α/β, and PP2A is formed upon treatment with the anti-cancer drug As2O3." (PMID 33672232, 2021). "In conditional mouse knockout studies, deletion of GSK-3β expression was postulated to be necessary for the establishment of myelodysplastic disease syndrome (MDS) while both GSK-3β and GSK-3α were shown to be necessary for progression to acute myeloid leukemia (AML)." (PMID 32365809, 2020). "For example, in acute myeloid leukemia (AML), GSK3α but not GSK3β suppresses c-myc and cyclin D1 to maintain stemness." (PMID 41300341, 2025).
pancreatic cancer (16 papers, 2009 to 2023). "Pancreatic cancer and hepatocellular carcinoma are two diseases linked to GSK3A." (PMID 36993785, 2023). "It has been shown that inhibition of GSK3α/β in pancreatic cancer cell (PCC) lines reduces NF-κB activity." (PMID 36499109, 2022). "GSK3α (glycogen synthase kinase 3 alpha), a key gene in pancreatic carcinoma, is upregulated by KRAS, which leads GSK3α to interact with transforming growth factor-beta activated kinase 1 (TAK1), activating IκB kinase complex (IKK), modulating NF-κB." (PMID 35684434, 2022). "For instance, there have been several reports that describe tumor supporting roles of GSK3α in glioblastoma, pancreatic cancer, multiple myeloma, and MLL-rearranged leukemia." (PMID 30679640, 2019). "The GSK3α/β inhibitor sensitivity of xenografts from primary and metastatic pancreatic cancer patients who progressed on chemo- and radiation therapies warrants further clinical investigation of GSK3α/β inhibitors as single agents or in combination." (PMID 30514931, 2018). "It has been shown that GSK-3α promotes oncogenic KRAS function via IKK-NF-κB activity in pancreatic cancer." (PMID 27049759, 2016). "PG545 dramatically decreased the levels of β-catenin, phosphorylation of GSK3α/β and its downstream target, Cyclin D1 in all tested pancreatic cancer cells (AsPC-1, MiaPaCa-2, and Capan-1) in a concentration-dependent manner." (PMID 25669977, 2015). "Recently, an elegant study from Albert Baldwin group demonstrated for the first time that GSK3α plays a predominant role in pancreatic cancer, as compared to GSK3β." (PMID 25714023, 2015). "To determine the effect of GSK-3 isoforms on NF-κB target gene expression in pancreatic cancer cells, we genetically depleted the expression of GSK-3α and GSK3β, alone or in combination, in PANC-1 cells using RNA interference." (PMID 19405981, 2009). "Importantly, the in vivo growth of three PDXs from primary chemo-naive, primary refractory, and metastatic refractory pancreatic cancer patients was inhibited by the GSK3α/β inhibitor SB." (PMID 30514931, 2018). "In this report, GSK3α promoted oncogenic K-Ras function in pancreatic cancer cells through stabilization of TGFβ activated kinase-1 (TAK1) and TAK1 binding partner interactions and subsequent NFκB activation, suggesting that both these isoforms may have unique roles in various cancers." (PMID 25714023, 2015). "In this study, human iPSCs reprogrammed from monocytes of healthy volunteers were cultured in a media containing 50% of the CM from human pancreatic cancer derived BxPC3 cells supplemented with a MEK inhibitor (AZD6244) and a GSK-3α/β inhibitor (CHIR99021)." (PMID 37181678, 2023). "GSK-3α has been shown to be a therapeutic target in multiple human cancers including AML, pancreatic cancer, and prostate cancer." (PMID 27049759, 2016). "These proteins promote cell invasion by influencing ERK1/2 and Glycogen Synthase Kinase 3α/β (GSK-3α/β) signaling; Src, ERK1/2, and AMP-activated protein kinase 1 (AMPK1) signaling; and alpha-actinin 4 (ACTN4) and p27 signaling in pancreatic cancer, respectively." (PMID 31080558, 2019). "Work from our lab has also shown that GSK3α activity activates both canonical and noncanonical NF-κB signaling, and that GSK3α activity supports the proliferation and survival of pancreatic cancer cells." (PMID 29874793, 2018). "In pancreatic cancer, GSK3A but not GSK3B induced constitutive noncanonical NF-kappa-B signaling by stabilizing nuclear p52, although upregulation of GSK3A and GSK3B caused by mutant K-ras resulted in activation of constitutive canonical NF-kappa-B43." (PMID 28630423, 2017). "Recently, our lab has shown that in pancreatic cancer KRAS utilizes GSK3α to promote both canonical and non-canonical NF-κB activation." (PMID 24955217, 2014).
pancreatic cancer (continued). "To better understand the role of GSK-3α and examine the critical genes affected by GSK-3α in lung cancer, we initially screened a subset of NF-κB target genes such as MYC, WT1, BIRC2, IL-9, HMOX1, and TERT, which were regulated by a pan-GSK-3 inhibitor AR-014418 in pancreatic cancer." (PMID 27049759, 2016).
Alzheimer disease (14 papers, 2007 to 2026). A progressive, neurodegenerative disease characterized by loss of function and death of nerve cells in several areas of the brain leading to loss of cognitive function such as memory and language. "Despite the termination of clinical trials for GSK3α/β inhibitors in Alzheimer's disease (AD) treatment, there is a pressing need for novel therapeutic strategies targeting GSK3α/β." (PMID 39287420, 2025). "Two isoforms, GSK3α and GSK3β, have been identified and both are ubiquitously expressed in the brain and GSK3β is increased in the post-mortem brain of Alzheimer’s disease patients." (PMID 37754222, 2023). "Glycogen synthase kinase 3 (GSK3α and GSK3β) are serine/threonine kinases involved in numerous cellular processes and diverse diseases including mood disorders, Alzheimer’s disease, diabetes, and cancer." (PMID 22792253, 2012). "The present study not only supports the importance of GSK3 kinases (including GSK3α and GSK3β) as critical nodes in the progression of Alzheimer's disease, but also emphasizes the central role of GSK3 in regulating intracellular trafficking." (PMID 20520769, 2010). "In a streptozotocin-induced astrocytotoxicity model for Alzheimer’s disease, memantine ameliorated BDNF and GDNF decline in astrocytes along with phosphorylation of IRS-1, Akt, and GSK-3α/β." (PMID 32782018, 2020). "Further study is required on the roles of GSK3α and GSK3β in neuronal physiology, especially in different forms of synaptic plasticity, as well as in GSK3-related diseases of the nervous system (e.g., Alzheimer’s disease, bipolar disorder)." (PMID 26207897, 2015). "Furthermore, the activity of GSK3α, but not GSK3β, is required for the production of amyloid-β in the brain of patients with Alzheimer's disease." (PMID 17683539, 2007).
atherosclerosis (14 papers, 2017 to 2025). A disease characterized by the build-up of fatty material and calcium deposition in the arterial wall resulting in partial or complete occlusion of the arterial lumen. "As previously observed, myeloid GSK3α deficiency attenuates the development of atherosclerosis at the aortic sinus in Ldr−/− mice." (PMID 39456687, 2024). "Recent studies from our lab have implicated GSK3α in the progression and development of atherosclerosis." (PMID 33672232, 2021). "GSK3α/β has been linked to several disorders and diseases, including cancer, bipolar mood disorder, diabetes, Alzheimer’s disease, and atherosclerosis." (PMID 33672232, 2021). "Several lines of evidence have implicated GSK3α/β in the development of atherosclerosis." (PMID 29848965, 2018). "Furthermore, bone marrow deficiency of AKT, an upstream regulator of GSK3α/β, has been found to modulate atherosclerosis development and macrophage polarization in mice." (PMID 29848965, 2018). "By contrast, GSK3α signaling regulates M1 macrophage polarization and promotes atherosclerosis development." (PMID 39880090, 2025). "ECs play a critical role in the initiation of atherosclerosis and little is known about the potential role of GSK3α/β in the endothelium." (PMID 36499109, 2022). "Targeting the ER stress–GSK3α/β pathway, either genetically or pharmacologically can attenuate the progression and development of atherosclerosis in a mouse model system." (PMID 36012557, 2022). "While roles for myeloid GSK3α/β in the development of atherosclerosis have been established, there is limited knowledge on the potential roles of endothelial GSK3α/β." (PMID 36499109, 2022). "Recent evidence from our laboratory suggests that impeding ER stress–GSK3α/β signaling attenuates the progression and development of atherosclerosis in mouse model systems." (PMID 36012557, 2022). "This suggests that endothelial/macrophage GSK3α is an important contributor to plaque accumulation, and supports previous findings that GSK3α and GSK3β display different functional roles in the context of atherosclerosis." (PMID 36499109, 2022). "Previous research has indicated that a whole body GSK3α knockout attenuates atherosclerosis in mice." (PMID 36499109, 2022). "This study suggests the possibility of using small molecules targeting GSK3α as a therapeutic tool in the treatment of atherosclerosis and AML." (PMID 33672232, 2021). "Together, these results suggest a role for myeloid-specific GSK3α in the development of atherosclerosis." (PMID 34394077, 2021). "Results from our lab suggest that myeloid deletion of GSK3α, pharmacological mitigation of ER stress (by 4 phenylbutyrate), or inhibition of GSK3α/β (by valproate) attenuates the progression of atherosclerosis." (PMID 34394077, 2021). "In the near future, it will be important to continue to test and validate the contribution of ER stress-GSK3α/β signaling to accelerated atherosclerosis, in both in vivo and in vitro systems." (PMID 29848965, 2018).